KLF2 (KLF transcription factor 2)
Diseases named in the same sentence as KLF2 in open-access papers (continued):
Sharing a sentence is not in itself a finding about the gene and the disease.
Burkitt lymphoma (1 paper, 2018). A rare form of malignant mature B-cell non-Hodgkin lymphoma. "Multiple KLF2 mutations have been described previously in eleven patients with HLC-c (n = 1), extra-nodal marginal zone lymphoma (=1), Burkitt lymphoma (n = 1), SMZL (n = 1) and diffuse large B cell lymphoma (n = 7), and in most cases, the KLF2 mutations were located on separated alleles." (PMID 29989027, 2018).
cardiac arrest (1 paper, 2017). Cessation of breathing and/or cardiac function. "After donor cardiac arrest for 30 min in vivo and 24 h cold storage ex vivo, the rat livers exhibited a significant reduction in KLF2 protein and mRNA expression after warm reperfusion compared with the normal control livers." (PMID 29348789, 2017).
cerebral infarction (1 paper, 2021). An ischemic condition of the brain, producing a persistent focal neurological deficit in the area of distribution of the cerebral arteries. "EVs- miR-26a inhibitor + oe-KLF2 significantly reduced cerebral infarction area compared with EVs- miR-26a inhibitor + oe-NC in mouse brain tissue slices." (PMID 34311651, 2021). "EVs-miR-26a inhibitor + oe-KLF2 significantly reduced the area of cerebral infarction compared to EVs-miR-26a inhibitor + oe-NC." (PMID 34311651, 2021). "TTC staining showed that compared with EVs-inhibitor-NC + oe-NC, EVs-inhibitor-NC + oe-KLF2 reduced cerebral infarct size, while EVs-miR-26a inhibitor + oe-NC increased the area of cerebral infarction." (PMID 34311651, 2021).
chronic heart failure (1 paper, 2022). "This neutrophil KLF2-NETosis-thrombosis mechanism underlying chronic heart failure can be exploited for therapeutic gain by therapies targeting neutrophils, NETosis, or thrombosis." (PMID 34793333, 2022).
colorectal tumor (1 paper, 2018). "In addition, immunohistochemistry analyses revealed that EZH2 was upregulated in colorectal tumor tissues, whereas KLF2 and CDKN2B expression was reduced in cancer tissues." (PMID 30266084, 2018).
Crohn disease (1 paper, 2023). A gastrointestinal disorder characterized by chronic inflammation involving all layers of the intestinal wall, noncaseating granulomas affecting the intestinal wall and regional lymph nodes, and transmural fibrosis. "As Itgβ7 is also a direct target gene of KLF2, it will be of great interest to study the effect of KLF2 loss-of-function mutations on the onset and progression of gut-related diseases, such as Ulcerative colitis and Crohn’s disease." (PMID 37251374, 2023).
depression (1 paper, 2019). "The FoxO and mTOR signaling pathways may be involved in the underlying mechanism of the antidepressant effects of ketamine, and Plin4, Sgk1, Klf2 and Dcaf12l1 may be potential biomarkers for depression in N-methyl-D-aspartic acid receptor antagonist treatment." (PMID 31281445, 2019). "Furthermore, the expression levels of Plin4, Sgk1 and Klf2 increased in the striatum samples of rat models of depression following administration of ketamine, and the expression of Dcaf12l1 decreased compared with the control group." (PMID 31281445, 2019). "However, to the best of the authors' knowledge, the association between Klf2 and depression or NMDA receptor antagonists has not been previously reported." (PMID 31281445, 2019). "The current study indicated that Plin4, Sgk1, Klf2 and Dcaf12l1 were differentially expressed in depression models treated with ketamine, phencyclidine and memantine, which suggested that these genes may be the targets of the NMDA receptor antagonist treatment." (PMID 31281445, 2019).
edema (1 paper, 2022). An abnormal accumulation of fluid beneath the skin, or in one or more cavities of the body. "It is known that klf2a klf2b double mutants (henceforth referred to as simply klf2 mutants in text) have increasing incidences of pericardial edema as they age from 2 dpf to 5 dpf." (PMID 35030171, 2022).
emphysema (1 paper, 2022). "Quantification of KLF4 and KLF2 staining data in these tissue sections suggest that in normal lung, the level of KLF2 is relatively lower than KLF4, in contrast, in emphysema and COPD tissue sections, the levels of KLF2 is higher than KLF4." (PMID 36425528, 2022). "Quantification showed that KLF4 expression was barely detectable in lungs from patients with emphysema and COPD, while the expression level of KLF2 clearly increased." (PMID 36425528, 2022).
endometriosis (1 paper, 2022). The growth of functional endometrial tissue in anatomic sites outside the uterine body. "NEAT1 and XIST may regulate the expression of four TFs (AEBP1, HOXB6, RORB, and KLF2) through the lncRNA-miRNA-mRNA network and participate in the development of endometriosis." (PMID 36532015, 2022). "Thus, HOXB6 and KLF2 were stable and valuable biomarkers across various models for endometriosis." (PMID 36532015, 2022). "Two of them, KLF2 and HOXB6, are critical molecules in the gene interaction network of endometriosis." (PMID 36532015, 2022). "AEBP1 and KLF2 were higher expressed, while DLX6, HOXB6, and RORB were lower expressed in endometriosis in the GSE7305 dataset." (PMID 36532015, 2022). "Then, two of four TFs (KLF2, HOXB6) repeat occurrence in the following multiple modules (String, WGCNA), implying dominant contribution to endometriosis." (PMID 36532015, 2022). "Using other machine learning approaches, both KLF2 and HOXB6 repeatedly appeared in Support Vector Machine Recursive Feature Elimination (SVM-RFE) and random forest models, implying their crucial role in endometriosis." (PMID 36532015, 2022). "Our analyses point to, HOXB6, KLF2, and RORB, maybe cross-regulatory genes in endometriosis and SLE." (PMID 36532015, 2022). "Besides, SVM-RFE and random forest algorithms identified that KLF2 and HOXB6 were the coincident genes, suggesting dominant contribution to endometriosis." (PMID 36532015, 2022). "In addition, three modules were established through Metascape, and KLF2 and HOXB6 genes were again present in two modules, implying important biomarkers in endometriosis." (PMID 36532015, 2022). "AEBP1, HOXB6, KLF2, and RORB may be potential biomarkers for endometriosis." (PMID 36532015, 2022). "The roles of KLF2 and RORB in endometriosis have not been explored." (PMID 36532015, 2022).
fungal infection (1 paper, 2022). "In this endeavor, we explored whether Notch was pivotal for the handling of this fungal infection in wild‐type mice independent of persistent changes in KLF2." (PMID 35603470, 2022).
histoplasmosis (1 paper, 2022). A disease caused by the fungus Histoplasma capsulatum. "We previously reported that a KLF2–Notch axis was key to restraining the differentiation and expansion of Th2 cells in histoplasmosis." (PMID 35603470, 2022).
HIV-1 infection (1 paper, 2021). The type species of lentivirus and the etiologic agent of acquired immunodeficiency syndrome (AIDS). "Aside from virus entry via KLF2-regulated CCR5 into naïve CD4+ T cells, HIV-1 infection itself represses Foxo-1 activity and KLF2 expression, resulting in the downregulation of L-Selectin (CD62L)." (PMID 34696279, 2021).
humoral immune deficiency (1 paper, 2022). "Although no serious effects on humoral immune deficiency were observed in experimental KLF2 deficiency models, the index patient (VI:2) with KLF2 variant fulfills the criteria for CVID." (PMID 36466816, 2022).
Hypercalcemia (1 paper, 2021). An abnormally increased calcium concentration in the blood. "The results showed that KLF2 expression in brain tissues and hypercalcemia-induced neurons of CKD mice was decreased, and CXCL1 expression was increased." (PMID 34462420, 2021). "Next, OGT silencing and CXCL1 overexpression were performed simultaneously in hypercalcemia-treated mouse neurons to further verify the effect of the OGT/EZH2/KLF2/CXCL1 axis on hypercalcemia-induced neurotoxicity." (PMID 34462420, 2021). "Silencing OGT attenuated hypercalcemia-induced neurotoxicity by regulating the EZH2/KLF2/CXCL1 axis." (PMID 34462420, 2021). "Our mechanistic study further revealed that EZH2 could promote the expression of CXCL1 in primary neurons by inhibiting KLF2, thereby promoting the toxicity of primary neurons induced by hypercalcemia." (PMID 34462420, 2021). "Silencing OGT reduced the hypercalcemia-induced toxicity of neurons by inhibiting the expression of EZH2, which elevated the expression of CXCL1 in primary neurons by diminishing KLF2." (PMID 34462420, 2021). "In order to verify our hypothesis on whether EZH2 promoted CXCL1 expression in primary neurons by downregulating KLF2, we first detected the protein expression of KLF2 and CXCL1 in brain tissues and hypercalcemia-induced neurons of CKD mice." (PMID 34462420, 2021).
hypertensive nephropathy (1 paper, 2022). Kidney damage that results from chronically elevated blood pressure; complications include glomerular damage resulting in proteinuria and hematuria. "We aim to conduct a study in the future to investigate the upregulation of KLF2 expression and the mechanism underlying its protective effect on hypertensive nephropathy using a fluidic environment that is more similar to blood flow." (PMID 35269384, 2022). "We performed an immunohistochemical assay of KLF2 in biopsied kidney tissue from both the normal control and hypertensive nephropathy groups." (PMID 35269384, 2022). "Immunohistochemical staining showed that KLF2 expression was decreased in kidneys with hypertensive nephropathy compared to that in normal kidneys (p < 0.05)." (PMID 35269384, 2022). "Our study suggests that the upregulation of KLF2 expression is a potential therapeutic strategy against hypertensive nephropathy." (PMID 35269384, 2022). "The percentage of KLF2 expression was significantly lower in hypertensive nephropathy (1.5 ± 0.9%, n = 9) than in the control group (3.5 ± 2.5%, n = 8, p < 0.05)." (PMID 35269384, 2022). "In the present study, we used a novel machine to identify the role of KLF2 in human primary glomerular endothelial cells (hPGECs) in an in vitro model of hypertensive nephropathy." (PMID 35269384, 2022). "Our results also showed that the apoptosis and fibrosis of glomerular endothelial cells were increased by hypertensive injury, suggesting that a decrease in the KLF2 expression of glomerular endothelial cells may be one of the mechanisms of hypertensive nephropathy." (PMID 35269384, 2022). "However, no studies have evaluated the role of KLF2 in hypertensive nephropathy using hPGECs." (PMID 35269384, 2022). "However, to date, there have been no studies on the role of KLF2 in hypertensive nephropathy." (PMID 35269384, 2022).
intestinal tumor (1 paper, 2010). "For example hemizygous KLF2 mice have altered atherosclerotic risk and haploinsufficiency of KLF4 results in increased intestinal tumor formation." (PMID 20454664, 2010).
ischemia (1 paper, 2020). A hypoperfusion of the BLOOD through an organ or tissue caused by a PATHOLOGIC CONSTRICTION or obstruction of its BLOOD VESSELS, or an absence of BLOOD CIRCULATION. "Mice were subjected to 45 min of ischemia followed by reperfusion, and KLF2-EVs were administrated through intravenous injection." (PMID 33052233, 2020).
lentivirus infection (1 paper, 2021). Virus diseases caused by the Lentivirus genus. "The protein and mRNA levels of KLF2 and NF-κB (p65) in the brain tissues were measured by western blot and qRT-PCR assays after lentivirus infection." (PMID 34141823, 2021). "KLF2 was overexpressed in the rats with ICH-like symptoms by lentivirus infection." (PMID 34141823, 2021).
Marfan syndrome (1 paper, 2025). A disorder of the connective tissue. "Genetic loss of TGF-β signaling significantly slowed myxomatous changes, but blockade of monocyte recruitment failed to prevent myxomatous changes conferred either by loss of KLF2/4 or by expression of the mutant FBN1 C1039G protein associated with Marfan syndrome." (PMID 40519164, 2025). "In the Fbn1C1039G/+ mouse Marfan syndrome model, expression of valve endothelial Klf2/4 was unchanged in comparison with control tissue." (PMID 40519164, 2025).
myeloproliferative disorder (1 paper, 2013). A clonal hematopoietic stem cell disorder, characterized by proliferation in the bone marrow of one or more of the myeloid (i.e., granulocytic, erythroid, megakaryocytic, and mast cell) lineages. "KLFs 4, 5 and 10 are important in T-cell activation and trafficking and KLF4 may function as a tumor suppressor in adult T-cell leukemia, KLF2 promotes memory B-cell differentiation and KLF3-deficient mice display a myeloproliferative disorder." (PMID 24130502, 2013).
neuropathic pain (1 paper, 2022). Chronic pain caused by damage to nerve fibers. "A novel KLF2/lncRNA SNHG12/miR-494-3p/RAD23B axis might provide new insight for developing novel diagnosis or therapeutic targets for neuropathic pain." (PMID 35624111, 2022).
Niemann-Pick disease (1 paper, 2019). A group of inherited, severe metabolic disorders in which sphingomyelin accumulates in lysosomes in cells. "Finally, we sought to test if induction of KLF2 and ETV1 in ASM-deficient cells contributes to Niemann Pick disease pathology or if it is a protective mechanism." (PMID 30775969, 2019). "The publicly-available transcriptome datasets used in this study are GSE39621 for Niemann-Pick's disease mouse model (Npc1-/-) and GSE27602 for Klf2-/-mice." (PMID 30775969, 2019).
oral cancer (1 paper, 2009). "In the present study, we demonstrated the novel transcriptional regulation of CXCR4 via the transcription factor KLF2 in vesnarinone-treated oral cancer cells." (PMID 19671192, 2009). "Our results indicated that vesnarinone downregulates CXCR4 expression via the upregulation of KLF2 in oral cancer." (PMID 19671192, 2009).
orchitis (1 paper, 2021). Inflammation of one or both testes due to viral or bacterial infections. "On the other hand, Klf2, Klf4, Nfe2l2/Nrf2, Id1, Id2, Rad21, Xrcc1, and Cycs were found to be negatively correlated with androgen synthesis during orchitis." (PMID 35111154, 2021).
ovarian tumor (1 paper, 2023). "SP1 up regulated the SNHG7 that interacted with EZH2 to inhibit KLF2 expression in ovarian tumor cells." (PMID 37807067, 2023). "KLF2 recruited the SP1/CPBP to down regulate the WEE1 that sensitized ovarian tumor cells toward the DNA damage mediated apoptosis." (PMID 37807067, 2023).
prostate tumor (1 paper, 2024). "Therefore, KLF2 may be a prostate tumor suppressor gene, and its downregulation is likely due to aberrant miR-15b-3p overexpression." (PMID 38495481, 2024).
renal cell carcinoma (1 paper, 2023). "For example, decreased KLF2 attenuated ferroptosis in renal cell carcinoma by regulating GPX4 level." (PMID 37874682, 2023).
schizophrenia (1 paper, 2024). A major psychotic disorder characterized by abnormalities in the perception or expression of reality. "There are also agonists or activators for products of six DEGs that are down-regulated in ASD (Lrrk2), schizophrenia (Chrm4, Prkca), schizophrenia and BP (Klf2) or schizophrenia, BP and MDD (Nr4a1 and Nr4a3)." (PMID 39502833, 2024).
serous ovarian tumor (1 paper, 2020). "With regard to KLF2, previous studies reported a reduction in transcript levels in a series of 23 serous ovarian tumor specimens when compared to eight normal ovaries, and in vitro results suggested a role for KLF2 as a tumor repressor." (PMID 33250051, 2020).
sphingomyelinase deficiency (1 paper, 2019). "Our data in cellular and mouse models of Niemann-Pick-C disease and acid sphingomyelinase deficiency shows, however, that in addition to defective autophagy there is a signaling mechanism based on the induction of two transcription factors, KLF2 and ETV1, which repress mitochondrial biogenesis." (PMID 30775969, 2019).
subarachnoid haemorrhage (1 paper, 2021). "Additionally, another study elucidated that the up‐regulation of KLF2 was a promoter of neurological function recovery in rats with subarachnoid haemorrhage." (PMID 33951295, 2021).
Thrombocytopenia (1 paper, 2024). A reduction in the number of circulating thrombocytes. "Focusing on KLF2 may become a valuable strategy for treating diseases associated with thrombocytopenia." (PMID 39014479, 2024). "Our findings identify KLF2 as a key regulator of megakaryopoiesis, expanding our understanding of the molecular mechanisms in megakaryocytic differentiation and yielding possible new ideas for the intervention in thrombocytopenia." (PMID 39014479, 2024).
thrombosis (1 paper, 2023). "Peter and colleagues have indicated that endothelial-derived KLF2 maintains blood flow and vasoreactivity and alleviates vascular inflammation and thrombosis." (PMID 36632224, 2023).
thrombotic microangiopathy (1 paper, 2013). The syndromes of microangiopathic hemolytic anemia, thrombocytopenia, and variable signs of organ impairment, due to platelet aggregation in the microcirculation. "For example, in renal transplants with thrombotic microangiopathy, studies of gene expression in the glomerulus have demonstrated a downregulation of KLF2 and subsequent upregulation of genes that inhibit local fibrinolysis." (PMID 24396594, 2013).
thyroid tumor (1 paper, 2024). A benign or malignant neoplasm affecting the thyroid gland. "Furthermore, we integrated public dataset and compared the co-stimulatory scores as well as the expression levels of KLF2 of DCs among various thyroid tumors." (PMID 39030177, 2024).
uremia (1 paper, 2023). A clinical syndrome associated with the retention of renal waste products or uremic toxins in the blood. "Thus, chronic accumulation of uremic toxins and inflammatory mediators in USP can lead to a loss of protective anti-inflammatory KLF2 expression in ECs exposed to uremia." (PMID 37795100, 2023). "First of all, we found that endothelial KLF2 expression is strongly downmodulated by uremia compared to healthy serum." (PMID 37795100, 2023). "Uremia downmodulates vasculoprotective KLF2 in endothelium, leading to detrimental vascular inflammation, while MCO dialysis with the novel improved HDx therapy approach can maintain physiological levels of vasculoprotective KLF2." (PMID 37795100, 2023). "In this study, we have investigated in detail the effect of uremia-induced regulation of KLF2 on the impact of pro-inflammatory mediators and endothelial function." (PMID 37795100, 2023). "However, the potential role of KLF2 in uremia-induced endothelial inflammation, maladaptation, and dysfunction has not been studied in detail yet." (PMID 37795100, 2023). "Thus, targeting the modulation of endogenous KLF2 expression (or its activity) could motivate novel therapies to treat the vascular microinflammation induced by uremia." (PMID 37795100, 2023). "Indeed, targeted deletion analysis in our study indicates that AP-1 and the constitutive element c-FOS rather than c-JUN bind to the KLF2 promoter sequence -464 to -441 to regulate the inhibition of KLF2 in uremia." (PMID 37795100, 2023).